AHSG (alpha 2-HS glycoprotein)
Diseases named in the same sentence as AHSG in open-access papers (continued):
Sharing a sentence is not in itself a finding about the gene and the disease.
tumor (30 papers, 2014 to 2026). "Random Forest followed by Boruta analysis confirmed that alpha-2-HS-glycoprotein (P02765) was an independent variable for tumor-associated hearing loss." (PMID 29856847, 2018). "Random Forest and Boruta methodology, confirmed that Alpha-2-HS-glycoprotein (P02765) was an independent variable for tumor-associated hearing loss." (PMID 29856847, 2018). "Alpha-2-HS-glycoprotein, P02765, was shown to be an independent variable for tumor-associated hearing loss, a finding that needs to be verified in other studies." (PMID 29856847, 2018). "Furthermore, Random Forest and Boruta analysis showed that alpha-2-HS-glycoprotein, P02765, was an independent variable for tumor-associated hearing loss." (PMID 29856847, 2018). "Metabolism-related genes such as AHSG, ALB, and APOE gradually increased in expression during the mid-late stage of development, indicating their stronger association with abnormal tumor metabolism." (PMID 38230205, 2024). "Previous studies have shown that a high expression of C3, TIMP-1, and AHSG genes in tumors can promote tumor cell proliferation and tumor deterioration." (PMID 35935258, 2022). "Meanwhile, the hub genes from the DEGs between T and LM groups (ALB, FGG, AHSG, TF, and GC) also showed marked alterations in the correlations, indicating potential mechanisms involved in the tumor metastasis." (PMID 32496505, 2020). "Combination models showed that tumor stage and two prognostic markers, alpha-2-HS-glycoprotein and apolipoprotein CIII, had a similar effect on the prognosis of HCC." (PMID 32845921, 2020). "Fetuin-A (AHSG) has been studied for the past ~74 years, and yet, its potential role in tumor progression is just beginning to be appreciated." (PMID 30060600, 2018). "As for CRC, serum alpha-2-HS-glycoprotein inhibits tumor progression by blocking transforming growth factor-β1 (TGF-β1) binding to cell surface receptors, suppressing TGF-βsignal transduction, and inhibiting TGF-β-induced epithelial-mesenchymal transition." (PMID 24618180, 2014). "Alpha-2-HS-glycoprotein (P02765) was confirmed by nonlinear multivariate methods Random forest and Boruta as an independent variable for tumor-associated hearing loss." (PMID 29856847, 2018). "The upregulated expression of these miRNA was found to be identical to the downregulated expression of AHSG, F2, and TTR, thereby proving the potential miRNA-dependent regulation of AHSG, F2, and TTR expressions in tumor samples." (PMID 36224755, 2022). "In conclusion, suppression of DAPK1 may accelerate tumor growth and result in the upregulation of C3, TIMP-1, and AHSG expression and downregulation of KNG1 expression." (PMID 35935258, 2022). "Among the other hepatokines investigated in our study, high levels of AHSG, IGFBP1 and IGFBP-2 are found in the serum and HCC tissues of patients, whereas LECT2 expression is usually decreased and appears to behave as a tumour suppressor under the control of beta-catenin in the liver." (PMID 35409319, 2022). "Furthermore, our immunohistochemical staining confirmed that AHSG was negatively expressed in ESCC tumor and non-tumor tissues (data not shown), indicating that the alteration of this fragment might reflect a hypothetical reduction in protease activity in ESCC patients." (PMID 26993605, 2016).
cancer (25 papers, 2012 to 2025). A tumor composed of atypical neoplastic, often pleomorphic cells that invade other tissues. "Alpha-2-HS-glycoprotein promotes the growth of proliferative activity, adhesion and chemotaxis of cancer cells, thereby accelerating the development of metastatic lesions." (PMID 37509426, 2023). "Among them, TIMP1, LGALS3BP, A2M, AHSG, FN1, HRG, and ITIH4 have been associated with cancer, while CF I, C2, and C4A, have been related to complement activity." (PMID 37685286, 2023). "Exosomal extracellular matrix protein 1 (ECM1) 87 and Alpha-2-HS-glycoprotein (AHSG) 88 respectively promote cancer progression and invasion in most tumors." (PMID 34234872, 2021). "It should also be noted that TTR and KNG1 were also expressed and suppressed in other types of cancer, while AHSG and F2 were only expressed in CCA and liver hepatocellular carcinoma and only suppressed in CCA, which indicates that AHSG and F2 have higher specificity." (PMID 36224755, 2022). "It is notable that a recent bioinformatic study reported the DNA methylation of AHSG and F2 also increased in CCA patients, meaning that it may be another molecular mechanism for decreasing RNA levels of AHSG and F2 in cancer." (PMID 36224755, 2022).
kidney disease (19 papers, 2010 to 2024). "Some candidate biomarkers for kidney disease also exhibited high variations, such as beta-2-microglobulin (1.26), zinc alpha-2-glycoprotein (0.98) and alpha-2-HS-glycoprotein (0.84)." (PMID 26222143, 2015).
infection (12 papers, 2011 to 2025). The state of being infected such as from the introduction of a foreign agent such as serum, vaccine, antigenic substance or organism. "Importantly, the observed increased IFN-γ production was abrogated in fetuin-A-deficient AHSG mice suggesting that IFN-γ induction following Cm infection is fetuin-A dependent." (PMID 35498397, 2022). "We identified one protein (alpha-2-HS-glycoprotein, AhsG) with increased abundance during infection compared to two proteins (murinoglobulin-2, Mug2; major urinary protein 18, Mup18) with increased abundance in the uninfected state at 1 dpi (1 dpi Infected vs. Uninfected)." (PMID 41061967, 2025). "As expected, no fetuin-A was detected in AHSG mice with or without Cm infection." (PMID 35498397, 2022). "Similarly, levels of Transferrin, Afamin, Fetuin A (Alpha-2-HS Glycoprotein), Fetuin B and Transthyretin were reduced in both infection types, and no statistical difference was found between their levels." (PMID 30774579, 2019).
immune disorders (2 papers, 2021). "Genes (IL6R, AHSG, and other cluster-specific DEGs) in HCC4 (cluster 4) were enriched in phosphatase activity and downregulated process related to immune disorders." (PMID 33462196, 2021).
neurological disease (2 papers, 2018 to 2021). "Among the affected genes after OGD/R in human cerebral organoids, transthyretin (TTR), alpha-2-HS-glycoprotein (AHSG), and fibrinogen gamma chain (FGG) were found to be related to neurological disease." (PMID 34168538, 2021).
AHSG also shares sentences with these, for which no sentence is quoted: type 2 diabetes (82 papers); atherosclerosis (46); metabolic disorders (43); calcification (24); coronary artery disease (23); acute kidney injury (18); Hypertension (17); myocardial infarction (15); malnutrition (14); diabetic nephropathy (13); endothelial dysfunction (13); Hyperglycemia (12); steatosis (12); peripheral arterial disease (11); end-stage renal disease (10); Impaired glucose tolerance (9); Abdominal obesity (8); coronary artery calcification (8); hyperphosphatemia (8); liver fibrosis (8); hyperlipidemia (7); multiple sclerosis (7); rheumatoid arthritis (7); Alzheimer disease (6); colorectal cancer (6); Glucose intolerance (6); kidney stones (6); polycystic ovary syndrome (6); renal failure (6); bone disorder (5).
A further 196 diseases each share a sentence with AHSG in 5 papers or fewer.